LINC00623 (long independently transcribed non-coding RNA 623)
Gene: Long non-coding RNA gene on chromosome 1 (120,912,108 to 121,014,953, forward strand). Ensembl gene ENSG00000226067.
Diseases named in the same sentence as LINC00623 in open-access papers:
LINC00623 is named in the same sentence as 6 diseases in open-access papers, as found by Europe PMC text mining. Sharing a sentence is not in itself a finding about the gene and the disease. The quoted sentences say what the papers report.
breast carcinoma (1 paper, 2023). "A previous study indicated that LINC00623 plays important roles in regulating the progression hormone-related cancers, including lung cancer, prostate cancer and breast cancer." (PMID 37156816, 2023).
kidney cancer (1 paper, 2021). Primary or metastatic malignant neoplasm involving the kidney. "In addition, abnormal LINC00623 expression has also been correlated to poor survival of BrCa and kidney cancer patients." (PMID 33918195, 2021).
pancreatic ductal adenocarcinoma (1 paper, 2024). An infiltrating adenocarcinoma that arises from the epithelial cells of the pancreas. "In pancreatic ductal adenocarcinoma, the LINC00623\/NAT10 signaling axis promotes cell proliferation, tumorigenicity, migration and invasion." (PMID 38233839, 2024).
cancer (2 papers, 2022 to 2023). A tumor composed of atypical neoplastic, often pleomorphic cells that invade other tissues. "LINC00623 has been shown to significantly correlate with OS as a potential new molecular biomarker and performs critical functions in the modulation of hormone-related cancer progression." (PMID 35422758, 2022).
LINC00623 also shares sentences with these, for which no sentence is quoted: lung carcinoma (1 paper); prostate carcinoma (1).